IGF2BP2 (insulin like growth factor 2 mRNA binding protein 2)
Diseases named in the same sentence as IGF2BP2 in open-access papers (continued):
Sharing a sentence is not in itself a finding about the gene and the disease.
thyroid cancer (26 papers, 2015 to 2026). "In this study, interrogation of TCGA thyroid cancer datasets revealed that the expression of IGF2BP2 was negatively associated with that of thyroid-specific iodine-handling genes." (PMID 35267576, 2022). "To evaluate the functional role of IGF2BP2 in thyroid cancer progression in vivo, we established xenograft models using IGF2BP2-knockdown CAL62 cells and control cells." (PMID 41522349, 2026). "To identify potential downstream effectors of IGF2BP2-driven dedifferentiation, we performed an intersection analysis of the DEGs across these two contrasting thyroid cancer models, TPC1-OE and CAL62-KD." (PMID 41522349, 2026). "In the present study, we emphasize the role of IGF2BP2 in facilitating thyroid cancer dedifferentiation and stemness sustaining." (PMID 41522349, 2026). "Collectively, these studies establish IGF2BP2 as a key oncogenic driver in thyroid cancer, however, they have examined PTC and ATC as separate entities without considering the continuous differentiation spectrum that characterizes thyroid tumors." (PMID 41522349, 2026). "To identify direct IGF2BP2 targets in thyroid cancer, we performed RIP-seq in TPC1 cells, revealing 3377 binding peaks across 1739 genes, predominantly localized near transcription termination sites (TES)." (PMID 41522349, 2026). "The pro-tumorigenic function of IGF2BP2 in thyroid cancer has been well documented in multiple studies." (PMID 41522349, 2026). "Taken together, our results showed that STAT1 was a dominant contributor responsible for the pro-dedifferentiation and tumor-promoting effects driven by IGF2BP2 in thyroid cancer." (PMID 41522349, 2026). "Generally, our data highlighted a crucial role for IGF2BP2 in driving both the dedifferentiation program and the maintenance of stemness properties in thyroid carcinoma at both transcriptional and translational levels." (PMID 41522349, 2026). "In thyroid cancer, IGF2BP2 is an oncogenic factor since it enhances the expression of the HAGLR lncRNA and the cellular proliferation." (PMID 35664076, 2022). "Then, IGF2BP2 was highly expressed in thyroid cancer, and MALAT1 was found to up-regulate IGF2BP2 and enhance MYC expression via m6A modification recognition by competitively binding to miR-204." (PMID 36281789, 2022). "LncRNA MALAT1 acts a oncogenic role in thyroid cancer by regulating the miR-204/IGF2BP2/m6A-MYC axis." (PMID 35676619, 2022). "MiR-204 up-regulates IGF2BP2 and enhances the expression of c-Myc through methylation recognition sites, which promotes the proliferation and invasion of thyroid cancer cells." (PMID 35022030, 2022). "MALAT 1 is known to bind to miR-204 by modifying and recognizing m6A, thereby up-regulating IGF2BP2 to facilitate the growth, migration, proliferation, and invasion of thyroid cancer cells." (PMID 35401751, 2022). "In these DEGs, RUNX2 was positively correlated with IGF2BP2 and negatively associated with NIS in thyroid cancer." (PMID 35267576, 2022). "Screening in multiple malignancies, IGF2BP2 was found to play oncogenic role in most of the malignancies including thyroid cancer." (PMID 35267576, 2022). "IGF2BP2 knockdown suppressed cell proliferation, migration, invasion, and induced cell apoptosis of thyroid cancer via by reducing the expression of long non-coding RNA HAGLR." (PMID 35002727, 2021). "LncRNA MALAT1 contributed to thyroid cancer progression through the upregulation of IGF2BP2 by binding to miR-204." (PMID 34917609, 2021). "Based on the TGCA database, IGF2BP2 expression was notably up-regulated in thyroid cancer relative to normal tissues." (PMID 35002727, 2021). "We found six RBPs (AZGP1, IGF2BP2, MEX3A, NUDT16, NUP153, USB1) independently associated with prognosis of patients with thyroid cancer according to univariate and multivariate Cox proportional hazards regression models." (PMID 33816259, 2021).
thyroid cancer (continued). "MALAT1 promotes thyroid cancer progression by binding to miR-204 and upregulating IGF2BP2, thereby affecting miR-204/IGF2BP2/m6A-MYC signaling." (PMID 34026852, 2021). "As gain-of-function mutations in NRAS are found in a minority of FVPTCs, overexpression of IGF2BP2 would be an intriguing alternative that leads to enhanced NRAS signalling in thyroid cancer with follicular histology." (PMID 25923053, 2015). "Here, we identified IGF2BP2 as a key m6A driver of thyroid cancer dedifferentiation and stemness." (PMID 41522349, 2026). "Similarly, IGF2BP2 expression was significantly upregulated in undifferentiated and poorly differentiated thyroid carcinomas within the GEO database, histological subtypes known for poor survival and treatment resistance." (PMID 41522349, 2026). "Given the observed association between dedifferentiation and enhanced stemness, we hypothesized that IGF2BP2 concurrently promotes cellular dedifferentiation and augments tumor stemness in thyroid carcinoma." (PMID 41522349, 2026). "Alternatively, IGF2BP2 was revealed to be targeted by miR‐204 in thyroid cancer." (PMID 36162823, 2023). "Although the function of IGF2BP2 in thyroid cancer was totally based on the public database analysis and did not reveal the underlying mechanism of the role of IGF2BP2, they do indicate that IGF2BP2 is a gene worthy of further analysis to account for the pathophysiological process of thyroid cancer." (PMID 35267576, 2022). "Furthermore, GSEA with transcriptome datasets of primary thyroid cancer samples showed that high IGF2BP2 expression was positively correlated to genes related to the cell cycle, tight junction, focal adhesion, and adherens junction pathways in cancer." (PMID 35267576, 2022). "Furthermore, we noticed that high expression of IGF2BP2 was associated with a good prognosis in THCA patients, which implies that IGF2BP2 might also play an important role in thyroid cancer." (PMID 33816259, 2021). "In conclusion, our study elucidates a novel thyroid-specific regulatory axis involving IGF2BP2 and STAT1 that drives dedifferentiation and enhances stemness in diverse subtypes of differentiated thyroid cancers." (PMID 41522349, 2026). "To elucidate the mechanism by which IGF2BP2 promotes thyroid cancer dedifferentiation, we performed RNA sequencing (RNA-seq) on TPC1 cells overexpressing IGF2BP2 (TPC1-OE) and CAL62 cells with IGF2BP2 knockdown (CAL62-KD)." (PMID 41522349, 2026). "In thyroid cancer, lncRNA HAGLR increases IGF2BP2 expression, and IGF2BP2 recognizes the m6A modification of c-MYC and leads to increased c-MYC expression, which promotes cancer progression." (PMID 35541906, 2022). "Specifically, this study revealed that, in thyroid cancer, MALAT-1 and insulin-like growth factor 2 mRNA binding protein 2 (IGF2BP2), a member of RNA binding proteins, were expressed while mir-204 was expressed poorly." (PMID 34445233, 2021). "The lack of longitudinal models, such as thyroid cancer organoid systems or time-resolved in vivo experiments, limits our ability to mechanistically dissect how IGF2BP2 orchestrates dedifferentiation during tumor evolution phases." (PMID 41522349, 2026). "The IGF2BP2-m6A-STAT1 complex is a master regulator of thyroid cancer dedifferentiation, establishing a novel therapeutic target for redifferentiation therapy in advanced thyroid cancer." (PMID 41522349, 2026). "However, in select cancers, such as OV (HR = 0.74, log-rank < 0.05) and thyroid carcinoma (THCA) (HR = 0.2, log-rank < 0.05), higher IGF2BP2 was correlated with increased survival." (PMID 40141058, 2025). "In thyroid cancer, MALAT1 targets miR-204, while IGF2BP2 is confirmed to be the target of miR-204." (PMID 35022030, 2022).
thyroid cancer (continued). "Most of the key m6A regulators were positively correlated to iodide-handling genes in thyroid cancer, but IGF2BP2, HNRNPC, WTAP, and RBM15B were negatively correlated to iodide-handling genes, and the correlation between IGF2BP2 and iodide-handling gene was the strongest." (PMID 35267576, 2022). "Likewise, the interfered STAT1 expression effectively counteracted the impact of IGF2BP2 inhibition in CAL62 cells, restoring proliferation and validating that STAT1 mediates the function of IGF2BP2 in promoting thyroid cancer dedifferentiation and CSCs features." (PMID 41522349, 2026). "Given the progressively increasing expression levels of IGF2BP2 across normal thyroid, PTC, PDTC, and ATC cell lines and tissues, we hypothesized that IGF2BP2 may contribute to the dedifferentiation phenotype in thyroid carcinoma." (PMID 41522349, 2026). "Hence, elevated‐IGF2BP2 could recognize m6A‐containing MYC and promote translation, exhibiting an oncogenic effect in thyroid cancer." (PMID 36162823, 2023).
cervical cancer (25 papers, 2020 to 2026). A primary or metastatic malignant neoplasm involving the cervix. "Consistently, Th17 numbers in cervical cancer biopsies correlated with IGF2BP2 expression associated with lymph node metastases and relapse." (PMID 41579022, 2026). "Mechanistically, the E6/E7 protein was found to regulate MYC mRNA m6A modifications through IGF2BP2, thus promoting cervical cancer cell aerobic glycolysis, proliferation, and metastasis." (PMID 39759516, 2024). "That study further highlighted the role of E6/E7 in promoting cervical cancer by activating IGF2BP2 and established a link with the promotion of aerobic glycolysis." (PMID 39759516, 2024). "Recently, it was reported that HR-HPV 16/18 infection in cervical cancer stabilized m6A-methylated MYC expression by regulating IGF2BP2, an m6A reader, further promoting aerobic glycolysis." (PMID 38784389, 2024). "For example, in cervical cancer, IGF2BP2 recognizes m6A modifications in circARHGAP12, which in turn promotes the stabilization of forkhead box M1 (FOXM1) mRNA." (PMID 39596216, 2024). "Mechanistically, IGF2BP2 recognizes the m6A site in circARHGAP12 and simultaneously enhances its enrichment, thereby promoting the proliferation and migration of cervical cancer." (PMID 39342406, 2024). "IGF2BP2 promotes cervical cancer fate by specifically binding to circRNAs and thereby regulating circRNAs." (PMID 39342406, 2024). "A decrease in the expression levels of IGF2BP1 and IGF2BP2 was also detected in Parkin‐overexpressing cervical cancer cells." (PMID 37877353, 2023). "By binding to a locus of the MYC gene, IGF2BP2 enhances the proliferation, metastasis, and aerobic glycolysis of cervical cancer cells." (PMID 36894952, 2023). "circARHGAP12 exerted the oncogenic role in cervical cancer progression through the m6A-dependent IGF2BP2/FOXM1 pathway." (PMID 36058934, 2022). "The long non-coding RNA miR22HG targeting IGF2BP2 as a tumor suppressor for cervical cancer will help us develop potential therapies for cervical cancer." (PMID 33952279, 2021). "Fluorescence in situ hybridization (FISH) assay illustrated that circARHGAP12 distributed in the cytoplasm of cervical cancer (CaSki) cells, and IGF2BP2 disperse both in the nucleus and cytoplasm." (PMID 34392306, 2021). "In conclusion, we found that circARHGAP12 exerted the oncogenic role in cervical cancer progression through m6A-dependent IGF2BP2/FOXM1 pathway." (PMID 34392306, 2021). "In summary, we unraveled a previously unknown molecular mechanism by which Th17 cells promote tumor progression under hypoxic conditions and suggest evaluation of Th17 cells as well as IGF2BP2 as potential target for therapeutic approaches in cervical cancer." (PMID 41579022, 2026). "Additionally, the downregulation of E6/E7 and IGF2BP2 expression has been shown to decrease aerobic glycolysis capacity and the growth of cervical cancer cells." (PMID 39759516, 2024). "Given that MYC is a downstream target of IGF2BP2 and a crucial regulator of glycolysis, further investigations revealed that E6/E7 can modulate aerobic glycolysis in cervical cancer cells through the m6A‐MYC pathway mediated by IGF2BP2 both in vitro and in vivo." (PMID 39660878, 2024). "In addition, miR22HG significantly promoted apoptosis and inhibited invasion of cervical cancer cells by targeting IGF2BP2." (PMID 33952279, 2021). "Moreover, MeRIP-PCR assay data revealed that the IGF2BP2 overexpression promoted the circARHGAP12 expression in cervical cancer (CaSki, SiHa)." (PMID 34392306, 2021). "Thus, our data suggest that circARHGAP12/m6A/IGF2BP2/FOXM1 axis in the cervical cancer tumorigenesis." (PMID 34392306, 2021). "Moreover, IGF2BP2 promotes the growth and metastasis of cervical cancer cells." (PMID 38665783, 2024).
cervical cancer (continued). "HK2 can be directly mediated by the m6A modifiers METTL3, YTHDF1, IGF2BP2, FTO and ALKBH5 in colorectal cancer and cervical cancer, leading to increased glycolysis, upregulated aerobic respiration in mitochondria and tumor progression." (PMID 41373022, 2025). "In cervical cancer, HPV E6/E7 can regulate aerobic glycolysis in cells through IGF2BP2-mediated m6A-MYC mRNA stabilization, thereby promoting cancer progression." (PMID 37932821, 2023). "For example, circARHGAP12 interacts with IGF2BP2 and contributes the stability of FOXM1 mRNA in cervical cancer." (PMID 35773744, 2022). "m6A-modified circARHGAP12 interacts with IGF2BP2 to enhance FOXM1 mRNA stability, forming circARHGAP12/IGF2BP2/FOXM1 complex, thereby promoting the proliferation and migration of cervical cancer cells." (PMID 34392306, 2021). "IGF2BP1 and IGF2BP2 are also regulated by Parkin, but we did not explore their ubiquitination modification or their role in the tumourigenesis of cervical cancer in the current study." (PMID 37877353, 2023). "In turn, IGF2BP2 modifies circRNA circARHGAP12 and enhances its ability to bind and stabilize the oncogene FOXM1, thus promoting tumor cell proliferation and migration in cervical cancer." (PMID 36072601, 2022). "In cervical cancer, gastric carcinoma proliferation enhancing transcript 1 (GHET1) regulates AKT/mTOR and Wnt/β-catenin signaling pathways by stabilizing the interaction of E2F6 and IGF2BP2." (PMID 32391379, 2020).
ovarian carcinoma (22 papers, 2009 to 2026). A malignant neoplasm originating from the surface ovarian epithelium. "In total, we found that mutation of ALKBH5 is only 1.5% in ovarian cancer, however, the mutation of IGF2BP2 accounts for 27% of ovarian cancer patients." (PMID 38637813, 2024). "In ovarian cancer cells, the RBP insulin-like growth factor 2 mRNA binding protein 2 (IGF2BP2) enhances the malignancy of ovarian cancer by boosting the expression of circular RNAs 0000745 (circ_0000745)." (PMID 40271197, 2025). "In ovarian cancer, circITGB6 directly interacted with IGF2BP2 and FGF9 mRNA, thereby stabilising FGF9 mRNA and inducing polarisation of TAMs towards M2 phenotype." (PMID 41399129, 2025). "Suppression of METTL3 and IGF2BP2 mRNA and protein levels.Reduced cell proliferation and migration for ovarian cancer models." (PMID 41157107, 2025). "TIMER2.0 and GSCA database were used to explore the immune analysis of ALKBH5 and IGF2BP2 in ovarian cancer." (PMID 38637813, 2024). "To deepen our understanding the role of ALKBH5 and IGF2BP2 play in ovarian cancer immune microenvironment, we used various databases to explore their relationships with immune cells, not only at tissues level, but also at single-cell level." (PMID 38637813, 2024). "We first found that ALKBH5 and IGF2BP2 were up-regulated in M2 macrophages, and both showed significantly correlated with immune cells in ovarian cancer, especially macrophages." (PMID 38637813, 2024). "According to our analysis, we found that ALKBH5 and IGF2BP2 were significantly correlated with the immune response in ovarian cancer." (PMID 38637813, 2024). "To explore the role of ALKBH5 and IGF2BP2 in immune cells at single-cell level in ovarian cancer, we found that ALKBH5 was widely expressed in immune cells, but its expression was highly expressed in macrophages." (PMID 38637813, 2024). "In this study, we found that among all the immune cells, ALKBH5 and IGF2BP2 showed the closest correlation with macrophages in ovarian cancer." (PMID 38637813, 2024). "Further validated the roles of ALKBH5 and IGF2BP2 played in ovarian cancer, GSCA software were used." (PMID 38637813, 2024). "In this study, we found that ALKBH5 and IGF2BP2 were up-regulated in M2 macrophages, which showed closely correlation with immune cells expressions in ovarian cancer, especially with macrophages." (PMID 38637813, 2024). "In cBioPortal database, we analyzed the copy number alterations of ALKBH5 and IGF2BP2 in ovarian cancer." (PMID 38637813, 2024). "In this study, we investigated the roles of m6A demethylase ALKBH5 and m6A recognition protein IGF2BP2 played in regulating macrophages polarization in ovarian cancer." (PMID 38637813, 2024). "For single-cell analysis, sc-TIME and HPA softwares were used to analyze the roles of ALKBH5 and IGF2BP2 played in immune cells in ovarian cancer." (PMID 38637813, 2024). "K-M plotter and TIMER2.0 databases were used to evaluate the prognostic role of ALKBH5 and IGF2BP2 in ovarian cancer." (PMID 38637813, 2024). "To investigate the prognostic role of ALKBH5 and IGF2BP2 played in ovarian cancer, we used the online K-M plotter database." (PMID 38637813, 2024). "The expression of ALKBH5 in distinct subtypes of ovarian cancer cells was also much higher than IGF2BP2, including differentiated, immunoreactive, mesenchymal and proliferative ovarian cancer." (PMID 38637813, 2024). "Next, we would like to investigate the correlation of ALKBH5 and IGF2BP2 with immune cells expression in ovarian cancer microenvironment." (PMID 38637813, 2024). "Here, we aimed to explore the role of m6A methylation enzymes ALKBH5 and IGF2BP2 in regulating macrophage polarization in ovarian cancer microenvironment." (PMID 38637813, 2024). "According to the study, IGF2BP2, KIAA1429, and YTHDF1 regulators are highly amplified in OC, and the majority of m6A genes, including METTL3, KIAA1429, HNRNPC, ZC3H13, and IGF2BP2, are upregulated in ovarian cancer tissues." (PMID 37194218, 2023).